CRP (C-reactive protein)
Diseases named in the same sentence as CRP in open-access papers (continued):
Sharing a sentence is not in itself a finding about the gene and the disease.
cancer (continued). "Therefore, we determined the association of serum CRP levels with night sleep (i.e., total sleeping time and restlessness were measured using a sheet-type non-wearable sensor) in non-imminent death and imminent death patients with advanced cancer who were admitted to a palliative care unit." (PMID 41302347, 2025). "PTX3, similar to CRP, is a key protein in innate immunity, tissue repair, and cancer-related processes." (PMID 41562853, 2025). "Among eight common cancer subtypes, we analyzed the relationship between CRP levels and the incidence of new-onset AF." (PMID 41387931, 2025). "Numerous biomarkers have been investigated to capture this cancer-related inflammatory state, including CRP, NLR, PLR, MLR, and SII, which have shown prognostic utility across different malignancies and disease stages." (PMID 40362613, 2025). "Fibrinogen and C-reactive protein are circulating proteins with increased levels in inflammatory states and cancers." (PMID 40149324, 2025). "Oncology is similarly rich in biomarkers, with some, like NSE and CRP, being critical for cancer diagnosis and prognosis." (PMID 41173049, 2025). "Lymphocyte count and C‐reactive protein (CRP) levels are routinely measured, with the CRP‐to‐lymphocyte ratio (CLR) serving as a prognostic marker in cancer." (PMID 40716028, 2025). "We assume that these models benefit from the fact that some markers (for example, CRP, ECOG PS) provide similar prognostic information across cancer types, allowing the model to translate learned associations from one cancer entity to another." (PMID 39885364, 2025). "Both scores highlighted the importance of inflammatory markers such as ESR, CRP and SKLC in cancer prediction, underscoring their potential as key indicators in assessing cancer risk among patients with NSS symptoms." (PMID 41371732, 2025). "This notion finds support in the elevated levels of inflammatory markers observed in cancer patients, including C-reactive protein (CRP), tumor necrosis factor α (TNF-α), and interleukins 2, 6, and 8, all linked to increased arrhythmic susceptibility." (PMID 41387931, 2025). "In the overall cohort of cancer patients, only serum concentrations of Ba and Factor H exhibited a moderate positive correlation with CRP levels." (PMID 40506552, 2025). "Several biomarkers have been proposed to predict the outcomes of cancer cachexia, including inflammatory markers such as C‐reactive protein (CRP), lymphocyte‐to‐CRP ratio (LCR) and the CRP‐to‐albumin ratio (CAR)." (PMID 41216846, 2025). "In response to the exacerbation, progression, and metastasis of inflammation in cancer tissues, the CRP concentration increases, whereas that of albumin decreases." (PMID 40144575, 2025). "The cancer surgery only subgroup analysis included six studies, and the CRP level was significantly lower in EA cohort (SMD = −0.72, 95% CI = −1.07 to −0.36, I2 = 63%, Egger’s regression p = 0.06, trim and fill reported no missing studies)." (PMID 40427164, 2025). "In cancer-associated inflammatory states, inflammatory cytokines such as IL-6 and TNF-α not only stimulate the synthesis of CRP but also inhibit the synthesis of albumin, accelerate its degradation, and promote vascular extravasation." (PMID 41415846, 2025). "In cancer patients, inflammatory markers like CRP, TNF-α, and interleukins are commonly elevated, reflecting an inflammatory state." (PMID 41387931, 2025). "Numerous studies have reported that cancer patients with elevated CRP levels tend to have poorer prognoses compared to those with normal CRP levels." (PMID 40786260, 2025). "The relationship between early-life undernutrition and both abnormal CRP and cancer incidence remained significant in all sensitivity models, demonstrating consistent trends." (PMID 40936900, 2025).
cancer (continued). "The role of the CRP is of significance, given that it has been identified as a potential mediator of carcinogenesis and cancer progression via the activation of the FcgRs/MAPK/ERK, FcgRs/NF-kB/NLRP3, and FcgRs/IL-6/AKT/STAT3 pathways." (PMID 40076898, 2025). "The inflammatory score derived from WBC and CRP z-scores is a powerful prognostic indicator in cancer patients, highlighting the critical role of systemic inflammation in cancer progression and nutritional deterioration." (PMID 40832638, 2025). "This was consistent with previous reports showing that CRP and Alb were negatively correlated in patients with cancer." (PMID 38965074, 2025). "One prospective study showed that the cancer incidence rate in patients with elevated circulating inflammatory markers (for example, C-reactive protein) during routine checkups was more than twice that of the control group." (PMID 40361340, 2025). "The clinical implications of serum CRP levels appear to vary with life expectancy in terminally ill patients with cancer." (PMID 41302347, 2025). "In contrast, the inflammatory score leverages two ubiquitously available, low-cost biomarkers (WBC and CRP) that capture systemic inflammation—a universal driver of cancer progression." (PMID 40832638, 2025). "The researchers correlated the release of serum biomarkers with cancer stage progression and the inflammatory marker C-reactive protein." (PMID 41303748, 2025). "LCR capitalizes on the balance between lymphocytes, which reflect the body's immune‐nutrition status and immune response to cancer, and CRP, an indicator of systemic inflammation driven by tumor activity." (PMID 40528380, 2025). "Although limited data exists regarding CRP direct interactions with glycoproteins in the context of cancer, its ability to directly bind proteins in the ECM is well-established and continuously advancing." (PMID 41614767, 2025). "The mean admission CRP levels of the patients with Stage 3-4 cancer were higher compared to those of the patients with Stage 1-2 cancer (p=0.005)." (PMID 40125102, 2025). "Future large-scale, prospective studies are needed to verify the potential of KL-6 as an early biomarker for ILD and further explore the relationship between CRP levels and cancer prognosis." (PMID 40771356, 2025). "Cancer cells can produce a number of chemokines and cytokines, which in turn results in an increase in the serum CRP level." (PMID 40076898, 2025). "We did not have reliable data on acute infection or chronic inflammatory conditions, but found a higher prevalence of a present/past history of cancer in the CRP ≥ 10 mg/L group compared with the CRP < 10 mg/L group." (PMID 41419753, 2025). "Our findings resemble the 1.6-fold excess cancer hazard reported among women prenatally exposed to the Dutch Hunger Winter and the heightened CRP levels seen in the Vietnamese 1944–45 famine cohort." (PMID 40936900, 2025). "In our comprehensive study involving 19,677 individuals with a cancer history, we conducted the first extensive systematic investigation into the relationship between CRP levels and the incidence of AF." (PMID 41387931, 2025). "The concentrations of presepsin, PCT, IL-6 and CRP were prospectively measured in 57 FN episodes in 23 cases of malignant haematological diseases in children." (PMID 40961458, 2025). "Inflammation also raises circulating levels of inflammatory cytokines that promote cancer, such as C-reactive protein (CRP) and interleukin-6 (IL-6)." (PMID 40007994, 2025). "Multivariable logistic regression models were constructed with oral frailty and dysgeusia as the primary exposures, with stepwise adjustment for PS, CRP, sex, and cancer stage." (PMID 41372876, 2025). "Patients with an increased number of metastases and previous cancer therapies and higher lactate dehydrogenase and C-reactive protein levels in blood at baseline were more likely to progress during the study." (PMID 39762422, 2025).
cancer (continued). "This is the reason why measurable serum parameters such as leukocyte count, platelet count, and C-reactive protein (CRP) are increased while albumin levels are decreased in patients carrying malignancy." (PMID 40941707, 2025). "The inflammatory score, integrating WBC and CRP, is a strong independent predictor of survival and nutritional deterioration in cancer patients." (PMID 40832638, 2025). "In patients with advanced cancer, elevated CRP levels are commonly experienced in conjunction with elevated levels of IL-1β and TNF." (PMID 40420174, 2025). "High CRP levels are also often prognostic of cancer incidence and advancement, with evidence showing CRP can facilitate tumor growth, metastatic behavior, chemoresistance, and immune evasion in various contexts." (PMID 41614767, 2025). "Inflammation-related biomarkers such as C-reactive protein (CRP), neutrophil-to-lymphocyte ratio (NLR), and PLR demonstrate significant associations with malignant tumors." (PMID 41346687, 2025). "C-reactive protein (CRP) is released in response to pro-inflammatory cytokines like interleukin-6 (IL-6), and is often elevated in cancer patients, thus serving as a marker of inflammation." (PMID 39940314, 2025). "The observed mediation effects are biologically plausible because serum CRP and WBC count were inversely associated with serum levels of most micronutrients examined and positively associated with all-cause, cancer, and/or cardiovascular mortality." (PMID 40023976, 2025). "In this study, we evaluated the prognostic value of a novel inflammatory and nutritional index—the NCR (Nutritional CRP Ratio)—in patients with cancer cachexia." (PMID 40133874, 2025). "C-reactive protein, another plasmatic inflammatory protein, has high levels in cancer and promotes metastasis and suppression of the immune response." (PMID 40149324, 2025). "Heterogeneity at post-intervention was moderate-to-high for CRP, IL-6, IL-6-CNS, IL-6-cancer, TNF-α, IL-10, IFN-γ, BDNF, and cortisol." (PMID 40281902, 2025). "CRP secretion from hepatocytes increases due to malignancy; thus, CRP is elevated, especially in almost all patients with malignant tumors." (PMID 40125102, 2025). "C-reactive protein is an inflammatory marker whose blood levels rise in infections, inflammatory states, injuries, and cancers." (PMID 40149324, 2025). "This is the first study of its kind to attempt to find a correlation in HNC patients prior to cancer diagnosis using pre-diagnosis CRP data." (PMID 40076898, 2025). "This index is defined as a combination of inflammatory markers such as C-reactive protein and neutrophil/lymphocyte ratio and is considered a potential tool for predicting clinical outcomes in a wide range of conditions from cancer to cardiovascular disease." (PMID 40579562, 2025). "Results remained similar after further adjustment for body mass index, C-reactive protein, arterial cardiovascular disease, and cancer." (PMID 39810988, 2025). "Within this study, the most frequent abnormal biomarkers among cancer patients were high inflammatory markers (CRP or ESR), low Hb, low albumin, low lymphocyte count and high ALP." (PMID 41371732, 2025). "The most significant finding of this study is that cancer patients experience the greatest improvement in C-reactive protein levels when following a KD for a duration of more than 12 weeks." (PMID 40756563, 2025). "Among healthy individuals, elevated CRP and other inflammatory cytokines Interleukin-1 (IL1) and IL6 are associated with increased risks of cardiovascular disease, cancer, and infections." (PMID 40475250, 2025). "Studies have shown that patients with cancer with elevated CRP levels tend to have a worse prognosis." (PMID 40786260, 2025). "A novel indicator, the CTI (which combines CRP and the TyG index to comprehensively assess the severity of inflammation and IR) is potentially valuable for predicting survival in cancer patients." (PMID 38965367, 2025).
cancer (continued). "CRP, one of the most reliable inflammatory marker is often elevated in many conditions including cancer." (PMID 41367907, 2025). "This indicates that systemic inflammation is a critical part of the pathophysiology of cancer cachexia and supports the inclusion of CRP-based inflammation assessments in the definition of cancer cachexia." (PMID 41294682, 2025). "The present multicenter cohort study provides compelling evidence that the inflammatory score, derived from baseline WBC and CRP z-scores, is a robust and independent predictor of survival and nutritional deterioration in cancer patients." (PMID 40832638, 2025). "In 82% of our cases, when there was an advanced or locally advanced stage of cancer, we presumed an increased CRP level." (PMID 40558585, 2025). "They identified 495 patients with hyperferritinemia; their mean age was 57 years, the median ferritin level was 9128 μg/L (range 5013–1,133,280 μg/L), median CRP was 104 mg/L (range 1–614 mg/L) and 78% of the patients had a history of cancer." (PMID 40565207, 2025). "In light of this possibility, it will be critical to assess what correlative relationship CRP has with KS-containing proteins in the TME of various cancers." (PMID 41614767, 2025). "Elevation of IL-6 and CRP are well-recognized features of cancer progression and considered predictors of poor prognosis and survival, and are found to be associated with chemotherapy resistance in breast, colorectal, lung, and gastrointestinal cancers." (PMID 40523478, 2025). "The cancer group had lower hemoglobin levels (10.7 g/dL vs. 11.1 g/dL, P < 0.001), and higher CRP levels (1.0 mg/dL vs. 0.8 mg/dL, P = 0.002) compared with the non-cancer group." (PMID 40729349, 2025). "mGPS is based on CRP and albumin levels, and a serum CRP concentration greater than 10 ng/mL is an important indicator of the prognosis of cancer or chronic disease." (PMID 40672827, 2025). "The acute-phase protein CRP is well-recognised as an indicator of cancer-induced systemic inflammation, which is often evident in clinical symptoms." (PMID 41306979, 2025). "This retrospective study aims to assess the predictive value of hs-CRP for the development of cancer in patients with CVD." (PMID 40004724, 2025). "Interleukin-6 (IL-6), which mediates Rb phosphorylation, is elevated in cancer patients with high CRP and low Alb levels." (PMID 38965074, 2025). "Numerous studies have demonstrated that inflammatory markers, such as C-reactive protein (CRP), neutrophil-to-lymphocyte ratio (NLR), and platelet-to-lymphocyte ratio (PLR), are associated with adverse prognosis in various cancer types." (PMID 40531914, 2025). "This was also supported by our mediation analyses, which showed that CRP, WBC count, total cholesterol, LDL cholesterol, and glucose levels together mediated around one‐fourth of the association between walking speed and cancer risk." (PMID 40275681, 2025). "The mean CRP levels at admission of the patients with Stage 3-4 cancer were significantly different compared to those of the patients with Stage 1-2 cancer." (PMID 40125102, 2025). "Other studies involving patients with cancer have shown increased CRP and LDH levels before death and highlighted their utility as prognostic indicators." (PMID 40924724, 2025). "Based on these findings, it is clear that basic blood tests like hemoglobin, CRP, and albumin can help screen for cancer in patients with thickened bowel walls seen on scans." (PMID 41011090, 2025). "CRP can be used as one of the most valuable indicators to evaluate the inflammatory state of cancer patients, and its elevated level reflects the inflammatory state of the body." (PMID 38562035, 2024). "Common blood tests were haemoglobin (24%, n = 7), C-reactive protein (17%, n = 5), and fasting blood glucose (17%, n = 5), and common cancers were pancreatic (29%, n = 8) and colorectal (17%, n = 5)." (PMID 38730644, 2024).
cancer (continued). "Elevated CRP emerges as a significant predictor of lower survival rates across various cancers, such as esophageal, colorectal, hepatocellular, pancreatic, urinary bladder, renal, ovarian, and cervical cancer, following surgical resection." (PMID 39001318, 2024). "The measure has been used with CRP in cancer patients: increasing levels of systemic inflammation were associated with worse symptoms, and patients reported worse outcomes." (PMID 39796678, 2024). "Markers of systemic inflammatory reaction (SIR), like C reactive protein (CRP), absolute neutrophil count (ANC) or lymphocyte count (ALC), or platelet count (APC), are often associated with poor prognosis in many cancer types, including CRC." (PMID 38645565, 2024). "CRP can be a useful tool when combined with other clinical information in optimizing the duration of antimicrobial treatment in a hospitalized cancer population." (PMID 39272020, 2024). "When looking at the nominal levels of the included blood test items using logistic regression, higher levels of ALAT, B12, ALP, bilirubin, LDH, CRP, GGT, creatinine and ESR were associated with increased odds of having cancer." (PMID 38409600, 2024). "Several studies have shown that subsequent CRP levels are usually decreased in cancer patients with solid tumors and treated infections." (PMID 38952546, 2024). "The majority of the studies were able to confirm the relationship between inflammation and end-points of cancer diseases and to disclose the prognostic value of the analysis of CRP, NLR, MLR, and other ratios or indices of inflammation-related cells." (PMID 38541074, 2024). "Associations have also been found between inflammation immune biomarkers, such as C-reactive protein (CRP), systemic immune-inflammation index (SII), Neutrophil to Lymphocyte Ratio (NLR), mean platelet volume (MPV) and cancer risk." (PMID 39020272, 2024). "CRP levels were comparable between the group with malignant tumors versus the control group (mean values 4.615 mg/dl versus 4.78 mg/dl)." (PMID 39655133, 2024). "Elevated levels of certain cytokines, such as interleukin-6 (IL-6) and C-reactive protein (CRP), have been linked to poorer outcomes in cancer patients receiving immunotherapy." (PMID 39335659, 2024). "Among them, CRP is an acute phase protein and a well-accepted biomarker of cancer-induced systemic inflammation, which has also been directly linked to tumor progression." (PMID 38291256, 2024). "The course of the disease is determined by proinflammatory cytokines such as interleukin-6 (IL-6) and C-reactive protein (CRP), as well as the existence of co-morbidities such as cardiovascular, respiratory, metabolic, and cancer." (PMID 39280382, 2024). "C-reactive protein (CRP) and cystatin C (CC) are also implicated in cancer progression and metastasis, highlighting the importance of investigating their role in CRC as well." (PMID 39001534, 2024). "The mGPS, consisting of C-reactive protein (CRP) and albumin, is one of the most extensively validated prognostic factors in some cancer types." (PMID 38987837, 2024). "Combined indices such as the AGR and CAR, which emphasize combinations of markers that directly reflect the cancer–nutrition relationship, including CRP, albumin, and globulin, have also been investigated in GBM." (PMID 39330000, 2024). "Elevated levels of PTH, BUN, and CRP in our cancer patients suggest an ongoing inflammatory state and altered metabolic balance, conditions previously identified as contributors to increased cancer risk in ESRD populations." (PMID 39712803, 2024). "Elevated CRP levels contribute to cancer progression by serving as a marker of disease advancement and enhancing inflammation, which supports tumor growth by aiding DNA damage, angiogenesis, and metastasis." (PMID 39132502, 2024).